BCL2 (BCL2 apoptosis regulator)
Diseases named in the same sentence as BCL2 in open-access papers (continued):
Sharing a sentence is not in itself a finding about the gene and the disease.
pancreatic cancer (continued). "Based on the well illustration of the role of Bcl-2 in cancer progression, we focused on the role of Claspin in celastrol-treated pancreatic cancer cells." (PMID 38110764, 2023). "Bcl-2 is known for enhancing the resistance of MIA-PaCa-2 pancreatic cancer cells to chemical agents." (PMID 37432179, 2023). "TLR4 was significantly overexpressed in pancreatic cancer cells and tissues and boosted the proliferation of pancreatic cancer cells by upregulating anti-apoptotic Bcl-2." (PMID 37904102, 2023). "In this study we did not verify which isoforms of the IL7 receptor were expressed that induce the upregulation of Bcl2 anti-apoptotic molecules in pancreatic tumor cells." (PMID 37381714, 2023). "Mechanistically, we demonstrated that celastrol-induced cellular proliferation inhibition and apoptosis in pancreatic cancer cells by downregulating Claspin and Bcl-2 expression in an m6A-YTHDF3-mediated manner." (PMID 38110764, 2023). "Our findings thus provided novel insights into the role of rutin in anti-pancreatic tumor treatment via the rutin-miR-877-3p-Bcl-2 axis and a promising therapeutic strategy for PC." (PMID 35408691, 2022). "Another example is the molecules miR-15a and miR-16-1, whose dysregulation allows prostate and pancreatic cancers to develop by influencing the signaling pathways associated with CCND1 (cyclin D1), WNT3A and BCL2." (PMID 35269947, 2022). "A similar mode of regulation by targeting Bcl2 was also observed in human gastric and pancreatic cancer cells." (PMID 36232799, 2022). "Restoring the level of miR-34 in pancreatic cancer downregulated the expression of Bcl-2 and Notch 1/2 and inhibited cell growth and invasion." (PMID 36232799, 2022). "In pancreatic cancer cells, GRh2 also induces apoptosis in Bxpc-3 cells by upregulating Bax, caspase-3, and caspase-9, and downregulating Bcl-2, survivin, cyclin D1, MMP-2, and MMP-9." (PMID 36313365, 2022). "Intriguingly, rutin significantly upregulated miR-877-3p expression to repress the transcription of Bcl-2 and to induce pancreatic cancer cell apoptosis." (PMID 35408691, 2022). "Treatment of pancreatic cancer cell line HPDE6-C7 with RP02-1 increased CASP3 activity and the BCL2-associated X apoptosis regulator (Bax) to BCL2 apoptosis regulator (Bcl-2) ratio but reduced chromatin condensation." (PMID 36364232, 2022). "Rutin upregulates miR-877-3p expression, inhibits Bcl-2 transcription and induces apoptosis in pancreatic cancer cells." (PMID 36325179, 2022). "In a previous study on pancreatic cancer, we reported that 125I seed implantation combined with gemcitabine improved the ratio of Bax/Bcl-2 in pancreatic cancer cells, yielding a clinically better anti-proliferation effect." (PMID 35692770, 2022). "The results of WB indicated that in the radioresistant pancreatic cancer cells, the cyclin D1, Bax, CDk4, cleaved caspase-3, Bcl-2, and γ-H2AX proteins were upregulated to varying degrees." (PMID 36276285, 2022). "Compound 2 induced remarkable apoptosis in human pancreatic tumor cells, characterized by the morphologies abnormity, the decrease in cell number and the ratio of Bcl-2 to Bax, in the 2-treated group compared with the control group." (PMID 36225350, 2022). "The pro-tumor effects of LONP1 can be partially attributed to LONP1-mediated regulation of Bcl-2 in melanoma, cyclin D1 in pancreatic cancer, and β-catenin in colorectal cancer." (PMID 35864539, 2022). "GEM can also induce reactive oxygen species, block the cell cycle and trigger apoptosis in pancreatic carcinoma cells by lowering the expression of Bcl-2 and activating caspases." (PMID 35454928, 2022).
pancreatic cancer (continued). "Gemcitabine can trigger apoptosis in pancreatic carcinoma cells by lowering the expression of Bcl-2 and activating caspases; it can also induce reactive oxygen species and block cell cycle in the S phase." (PMID 35454928, 2022). "Several clinical studies demonstrated that the higher level of Bcl-2 is related with a poor prognosis in many tumors' types, including pancreatic carcinoma and oral tongue squamous cell carcinoma." (PMID 36387351, 2022). "In conclusion, COL11A1 modulates apoptotic inhibition and chemoresistance in pancreatic cancer cells by activating the Akt/CREB/BCL-2/BAX signaling pathway." (PMID 33531986, 2021). "In conclusion, COL11A1 mediates apoptosis inhibition and chemoresistance in pancreatic cancer cells by activating the Akt/CREB/BCL-2/BAX signaling pathway." (PMID 33531986, 2021). "Combined treatment of metformin with aspirin suppresses Bcl-2 expression leading to induction of apoptosis in pancreatic cancer cells." (PMID 33849540, 2021). "A recent paper reported that DHA promotes the cell apoptosis of PANC-1 pancreatic cancer cells by inducing DNA fragmentation, activating caspase-3, and increasing the ratio of Bax/Bcl-2 via downregulating STAT3/nuclear factor (NF)-κB/cyclin D1 signaling." (PMID 33801246, 2021). "c-Myb, IGF-1R and Bcl-2 that are over-expressed in pancreatic cancer cells have a controlling role in cell proliferation, apoptosis, and differentiation." (PMID 33849540, 2021). "Due to the abnormal increase of NF-κB activity in pancreatic cancer, which leads to a large number of activation of the Bcl-2 promoter, eventually leading to the acceleration of cancer cell proliferation and the inhibition of apoptosis." (PMID 35222011, 2021). "Next, we observed that AktSer473/CREBSer133 activation by COL11A1 modulates the coordinated functions of BAX/BCL-2 in decreasing the apoptotic program in pancreatic cancer cells." (PMID 33531986, 2021). "The methylation of heat shock protein 70 by PRMT1 stabilized BCL2 mRNA and led to pancreatic cancer resistance to therapeutics." (PMID 34683150, 2021). "In the current work, we further revealed that COL11A1 inhibits apoptosis in pancreatic cancer cells by activating Akt/CREB/BCL-2 signaling." (PMID 33531986, 2021). "Western blot was used to detect the expression levels of pro-apoptotic caspase-3, BAX and anti-apoptotic Bcl-2, and the results confirmed that the miR-124 mimic tempted the apoptosis in pancreatic tumor cells, which was reversed by overexpression of EZH2." (PMID 33040049, 2020). "Luteolin treatment has been found to induce apoptosis in Bcl-2 overexpressing SW1990 pancreatic cancer cells via inhibiting Bcl-2 expression in a dose-dependent manner." (PMID 32717779, 2020). "Melatonin was involved in the necrosis and apoptosis of the pancreatic cancer cell line SW-1990 by modulating of the Bax/Bcl-2 ratio." (PMID 31013662, 2019). "The positive Bcl-2 expression showed as brown granules in human pancreatic cancer xenografts in nude mice, which mainly distributed in the cytoplasm." (PMID 31215421, 2019). "Meanwhile, they used multiple human pancreatic cancer cell lines and revealed that miR‐374b‐5p up‐regulation relieved the chemoresistance of pancreatic cancer cells to gemcitabine by targeting several antiapoptotic genes, such as BCL‐2, BIRC3 and XIAP." (PMID 30772950, 2019).
pancreatic cancer (continued). "BCL-2 is also dis-regulated in pancreatic cancer; therefore, BCL-2 has emerged as an important target for both prostate and pancreatic cancers therapies." (PMID 30991655, 2019). "The pancreatic cancer cell line PaTu 8988t showed a time-dependent decrease in the signal strength of Bcl2 after incubation with staurosporine up to the complete absence of proteins after 24 h of incubation (column 1)." (PMID 30686270, 2019). "According to another previous study, CCND1 and Bcl-2 concentrations are closely related to unfavorable prognosis and low survival rate of patients with pancreatic cancer." (PMID 31718693, 2019). "Further investigation revealed that orexin-A treatment activates theAkt/mTOR signaling pathway to promote cell proliferation byinhibiting Bcl-2/caspase-9/c-myc-mediated apoptosis in pancreatic cancer cells." (PMID 30429828, 2018). "We found that resveratrol and H2O2 markedly promoted the expression levels of Bax and suppressed the Bcl-2 level, which are proapoptotic and antiapoptotic molecules in pancreatic cancer cells, respectively." (PMID 29765509, 2018). "For assessing cell apoptosis in pancreatic cancer cells with Mfn2 overexpression, the expression of Bcl-2 and Bax was measured using Western blotting analysis." (PMID 30046371, 2018). "In high glucose conditions, we found upregulation of antiapoptotic gene Bcl-2 expression and downregulation of proapoptotic gene Bax expression; thereby, the changes demonstrate that high glucose inhibited apoptosis of pancreatic cancer cells." (PMID 30584464, 2018). "Consistent with our study results, the expression of PARP, cleaved caspase-3, and caspase-9 was obviously decreased in PHB under-expressing pancreatic cancer cell lines AsPC-1 and MiaPaCa-2, but Bcl-2 was apparently increased." (PMID 30185797, 2018). "Oleuropein and hydroxytyrosol arrested the cell cycle, increased the Bax/Bcl-2 ratio, increased activation of caspase 3/7 and induced apoptosis in pancreatic cancer cells (MIA PaCa-2)." (PMID 30004416, 2018). "Our results are consistent with presented information and indicated that 2.6 and 18 nm AgNPs-induced apoptosis associated with increased level of pro-apoptotic Bax protein and decreased level of anti-apoptotic Bcl-2 protein in pancreatic cancer cells." (PMID 29435134, 2018). "Mfn2 improved the expression of LC3-II and Bax and downregulated the expression of P62 and Bcl-2 in pancreatic cancer cells." (PMID 30046371, 2018). "Specifically, the apoptotic effect of DHA on growth of pancreatic cancer cells was first assessed by determining the apoptotic indices (cell viability, DNA fragmentation, ratio of Bax/Bcl-2, and caspase-3 activation)." (PMID 30400136, 2018). "Several compounds, notably 18, 20, 21, 23, and 24, displayed activity towards the pancreatic cancer cell lines BxPC‐3, known to overexpress Mcl‐1, and MiaPaCa‐2, which overexpresses both Mcl‐1 and Bcl‐2." (PMID 28670766, 2017). "We observed increased expressions of Bax, cleaved Caspase 3, cleaved Caspase 8 and cleaved PARP and while Bcl-2 expression was decreased in gedunin treated pancreatic cancer cells." (PMID 26988754, 2017). "Baicalein can promote pancreatic cancer cell apoptosis through up-regulating Bax and down-regulating Bcl-2 and Mcl-1, which has been reported by other groups." (PMID 28915595, 2017). "For example, miR-21 has been demonstrated to upregulate Bcl-2 in pancreatic carcinoma cells but downregulates Bcl-2 expression in breast and glioblastoma cancer cells." (PMID 28146427, 2017). "Based on the results that miR-329 induced cell apoptosis, we next performed western blot to evaluate the expression level of apoptosis related proteins such as cleaved Caspase-3, BAX and BCL2 in the pancreatic cancer cells overexpressing miR-329." (PMID 26885689, 2016). "In pancreatic cancer, miR-34 suppresses stem cell self-renewal via directly modulating the downstream targets Bcl-2 and Notch42." (PMID 26902416, 2016).
pancreatic cancer (continued). "On the other hand, the same study suggested BAX expression as a strong indicator of longer survival (P < 0.001) even when BAX and BCL2 were found to be overexpressed in pancreatic tumour cells." (PMID 27689078, 2016). "Preclinical studies have concluded that increased BCL2 expression correlated with apoptotic resistance and malignant phenotype in pancreatic cancer." (PMID 27689078, 2016). "Increased expression of pro-apoptotic proteins Bax, cleaved caspase-3, and cleaved PARP; in addition, decreased expression of anti–apoptotic protein Bcl-2 clearly demonstrate that nimbolide treatment inhibits pancreatic cancer growth by inducing apoptosis." (PMID 26804739, 2016). "We examined the antitumor effect of TRAIL on the six TRAIL-insensitive pancreatic cancer cell lines when combined with orally bioavailable Bcl-2 inhibitors, ABT-199 or ABT-263." (PMID 26506422, 2015). "MM41 is a quadruplex-interactive compound which binds strongly to the quadruplexes encoded in the promoter sequences of the BCL-2 and k-RAS genes, both of which are dis-regulated in many human pancreatic cancers." (PMID 26077929, 2015). "Metformin was reported to decrease SP1/SP3 expression and their downstream targets, such as Bcl-2, survivin, and cyclin D1, in pancreatic cancer cells." (PMID 26294325, 2015). "It has also shown that Bcl-2 confers resistance and Bax sensitizes to gemcitabine-induced apoptosis in pancreatic cancer cells." (PMID 25880226, 2015). "In the present study, we demonstrate that PM inhibits proliferation and induces apoptosis in pancreatic cancer cells by inhibiting the pro-survival Akt, NF-κB and mTOR signaling proteins and their downstream mediators as well as anti-apoptotic Bcl-2." (PMID 24603988, 2014). "Bcl-2 overexpression is also another common resistance mechanism precluding gemcitabine efficacy in pancreatic cancer." (PMID 23349858, 2013). "We found that treatment of pancreatic cancer cells with pristimerin resulted in an increase in the expression of Bax protein and a decrease in the expression of Bcl-2 and Bcl-xL thereby increasing the ratios of Bax/Bcl-2 and Bax/Bcl-xL in favor of apoptosis." (PMID 22952775, 2012). "Other tissue-based markers potentially relevant for pancreatic cancer include: p21, Bcl-2 and SMAD4." (PMID 22458520, 2012). "We now show that down-regulation of Cux1 in pancreatic cancer cell lines leads specifically to the transcriptional induction of the pro-apoptotic gene puma and the down-regulation of the anti-apoptotic gene Bcl-2." (PMID 22438831, 2012). "In pancreatic cancer cells, the simultaneous inhibition of BCL2, XIAP and survivin mediated induction of apoptosis." (PMID 22797576, 2012). "Previous studies also indicated that pancreatic cancer cells suppress the mitochondrial apoptotic pathway by overexpression of Bcl-2, Bcl-xL or XIAP to block the activation of caspases." (PMID 22246103, 2012). "Single investigated CpG of p16 (OR 10.4, 95%CI 2.0-54.7), BCL2 (OR 33.8, 95%CI 3.6-314.3), CD44 (OR 10.3, 95%CI 2.0-52.3) and TNFRSF10C (OR 11.8, 95%CI 2.2-64.1) were associated with pancreatic cancer." (PMID 22629410, 2012). "We also found that pristimerin decreased the expression of NF-κB-regulated gene product Bcl-2, Bcl-XL and cyclin D1 in pancreatic cancer cells, thus suppressed the growth of pancreatic cancer cells." (PMID 22952775, 2012). "In this study, we investigated the immunomodulatory effects of pan-Bcl-2 inhibitor AT-101 on pancreatic cancer (PC) cell cytotoxicity by activated T cells (ATC)." (PMID 23185240, 2012). "Fifth, overexpression studies in pancreatic cancer cells indicated that both caspase-8 (CrmA) and NF-κB-dependent mitochondrial proteins (Bcl-2, and Mcl-1) were involved in the process of TRAIL sensitization." (PMID 22829912, 2012). "In vitro studies has also revealed a direct correlation with high Bcl-2 cellular content and resistance to gemcitabine in pancreatic carcinoma cell lines." (PMID 23226540, 2012).
pancreatic cancer (continued). "Accordingly, the suppression of Bcl-2 using siRNA (small interfering RNA) restores gemcitabine sensitivity in pancreatic cancer cells." (PMID 21843371, 2011). "From literature search we identified the anti-apoptotic genes XIAP, Survivin and Bcl-2 as commonly upregulated in pancreatic cancer." (PMID 20646298, 2010). "This prospective study suggests SGLT1 and Bcl-2 as potential prognostic biomarkers for pancreatic cancer, although it should be validated by a more sensitive technique as qRT-PCR." (PMID 20706540, 2010). "In a few human tumors, high expression of Bcl-2 has been found, but the expression in pancreatic cancer cells is normal or even decreased." (PMID 24212603, 2010). "Defects in apoptotic pathways and the deregulation of apoptotic proteins, such as Survivin, Bcl-2, Bcl-xL and Mcl-1, play decisive roles in the development of pancreatic cancer." (PMID 24212603, 2010). "The deregulation of both the pro- and anti-apoptotic Bcl-2 proteins plays a crucial role both in the development, growth and expansion of pancreatic cancer and in the resistance to current therapy options." (PMID 24212603, 2010). "Overall, these data suggested a model in which Shh-Gli1 signaling controlled surviving state of pancreatic cancer cells by regulating Bcl-2 and IGF family in a parallel manner." (PMID 19736394, 2009). "On one hand, Shh-Gli1 signaling acts to inhibit apoptosis of pancreatic cancer cell by directly activating expression of Bcl-2 and indirectly decreasing the levels of Bax and Bak1." (PMID 19736394, 2009). "Apoptosis-associated proteins Bax, Bcl-2, BAD and survivin have all been demonstrated to be involved in the chemoresistance of pancreatic cancer cells and be regulated by FAK or Akt." (PMID 20021699, 2009). "QRT-PCR was performed to evaluate the levels Shh, Gli1, IGFBP6, IGF2, PCNA, Bcl-2, Bax and Bak1 mRNA in pancreatic cancer tissues (n = 6) and corresponding cancer side tissues (n = 6)." (PMID 19736394, 2009). "Our data demonstrate that miR-34 restoration can overcome chemo-/radioresistance of the pancreatic cancer cells that have high levels of Bcl-2 and low basal levels of miR-34s, and are dependent on Bcl-2 for survival and resistance to therapy." (PMID 19714243, 2009). "In conclusion, Gli1 directly facilitates expressions of IGFBP6 and Bcl-2 at the same time in cultured pancreatic cancer cells." (PMID 19736394, 2009). "In this study, we demonstrated that Gli1 protein bound to the promoters of IGFBP6 and Bcl-2 by XChIP-PCR assays, which suggested that Gli1 facilitates transcriptions of IGFBP6 and Bcl-2 in a parallel manner in pancreatic cancer cells." (PMID 19736394, 2009). "Restoration of miR-34 expression in the pancreatic cancer cells by either transfection of miR-34 mimics or infection with lentiviral miR-34-MIF downregulated Bcl-2 and Notch1/2." (PMID 19714243, 2009). "During a time kinetic from 24 to 72 h, DEX strongly enhanced the levels of MKP-1, SGK1 and X-IAP, in several pancreatic cancer cell lines examined, while Bcl-2 expression was only marginally increased." (PMID 16539710, 2006). "Of the various downstream targets of AKT, we examined activation of the NF-κB transcription factor and subsequent transcriptional regulation of BCL-2 gene family in pancreatic cancer cells." (PMID 12865934, 2003). "In pancreatic cancer, BCL-2 is frequently overexpressed and its overexpression confers chemo- and radioresistance and enhances tumorigenic and metastatic capability." (PMID 12865934, 2003). "Six (12%) pancreatic cancers were BCL-2 positive and demonstrated staining in the cytoplasm of carcinoma cells." (PMID 11953819, 2002). "Expression of BCL-2 was detected in 12% of pancreatic cancers and the sensitivity and specificity of immunostaining were confirmed by the prominent expression of BCL-2 in infiltrating lymphocytes in all cases examined." (PMID 11953819, 2002).